SLC40A1 (solute carrier family 40 member 1)
Diseases named in the same sentence as SLC40A1 in open-access papers (continued):
Sharing a sentence is not in itself a finding about the gene and the disease.
pneumonia (1 paper, 2026). An acute, acute and chronic, or chronic inflammation focally or diffusely affecting the lung parenchyma, caused by an infection in one or both of the lungs (by bacteria, viruses, fungi, or mycoplasma.). "Our computational-experimental pipeline prioritizes four biomarkers (NAMPT, NFKBIA, SLC40A1, PRKCQ) that stratify pneumonia risk and predict targeted drugs for therapeutic repurposing." (PMID 41557688, 2026). "Transcriptional profiling confirmed marked dysregulation of all four model genes (NAMPT, NFKBIA, SLC40A1, PRKCQ) in pneumonia cases versus controls (p < 0.001)." (PMID 41557688, 2026).
psoriasis (1 paper, 2024). An autoimmune condition characterized by red, well-delineated plaques with silvery scales that are usually on the extensor surfaces and scalp. "Our analysis revealed the upregulation of 3 ferroptosis markers (Chac1, Slc40a1, Fth1) and 29 ferroptosis drivers (including Alox12B and Alox15B, which encodes 15-LOX-2) as well as downregulation of 7 ferroptosis suppressors in psoriasis." (PMID 39570671, 2024).
tuberculosis (1 paper, 2020). A chronic, recurrent infection caused by the bacterium Mycobacterium tuberculosis. "In addition, SLC40A1 mRNA mean level in the elephants infected by tuberculosis was higher compared to the other elephants." (PMID 33195633, 2020).
vivax malaria (1 paper, 2015). "In this study population, the SLC40A1 SNP (744 G > T) was rarely detected and it did not influence vivax malaria outcomes." (PMID 26466783, 2015).
tumor (87 papers, 2012 to 2026). "High SLC40A1 expression is associated with enhanced macrophage-mediated tumor suppression and improved response to immunotherapy, highlighting its potential as both a prognostic biomarker and a therapeutic target." (PMID 41613134, 2026). "SLC40A1+ TAMs encoding iron transport proteins regulate chronic inflammation, facilitate tumor vascular and lymphatic formation through ECs and promote T cell exhaustion and impairment." (PMID 39232806, 2024). "SLC40A1 was highly expressed in tumor-associated macrophages and promoted proinflammatory cytokines in TME of HCC." (PMID 37575948, 2023). "Several studies have shown that C1QC and SLC40A1 macrophages are associated with the tumor microenvironment, and patients with high C1QC TAM gene signatures have the best prognosis." (PMID 36845083, 2023). "SLC40A1 is highly expressed in tumor-associated macrophages, which suppresses the production of IL-1β, and is consistent with low IL-1β expression in control myeloid cells." (PMID 35962439, 2022). "M2 macrophages, which resemble tumor-associated macrophages, express iron-efflux genes with increased SLC40A1 and decreased ferritin." (PMID 34389031, 2021). "The CXCL9+ TAMs and SLC40A1+ TAMs were enriched in peri-tumor region, and CXCL9+ TAMs showed the highest RO/E value of 3.41." (PMID 40230843, 2025). "C0 TNFRSF18+ TCs were found in all three tissues, C1 DAPL1+ TCs and C4 MEIS2+ TCs were more common in both normal and tumor tissues overall, and C2 SLC40A1+ TCs were most common in one of the tumor samples." (PMID 40612060, 2025). "In our study, the ferroptosis pathway in GSCs, mediated by REST, LRSAM1, and SLC40A1, was morphologically identified through immunohistochemical staining of orthotopic xenograft tumor specimens." (PMID 39039049, 2024). "CD200-CD200R1 contributing to tumor growth and progression indicates the pro-tumor function of SLC40A1+ TAMs by interacting with CD4-C4." (PMID 39232806, 2024). "CEACAM1-CD209 reveals the propelling role of SLC40A1+ TAMs in tumor angiogenesis and lymphangiogenesis." (PMID 39232806, 2024). "Vivo fluorescence imaging showed a significant reduction in tumor volume and size in mice treated with erianin in combination with TMZ, while GSCm01R cells overexpressing REST or SLC40A1 exhibited increased tumor volume and size." (PMID 39039049, 2024). "Our results showed that SNORD91A and SLC40A1 can induce local local immune microenvironment remodeling, further affecting tumor development." (PMID 37740815, 2023). "SLC40A1 deficiency was related to intracellular iron accumulation, and several studies demonstrated that inhibiting SLC40A1 significantly prevented tumor cell growth by inducing ferroptosis." (PMID 37728703, 2023). "For example, GBP2 activated caspase-4, that triggered cell death and inhibited tumor cell proliferation, and SLC40A1, that acted as a negative regulator of ferroptosis." (PMID 36899891, 2023). "In general, we for the first time demonstrate that miR-4735-3p facilitates ferroptosis and tumor suppression in ccRCC by targeting SLC40A1." (PMID 35646516, 2022). "Various studies have demonstrated that inhibiting SLC40A1 significantly prevented tumor cell growth by inducing ferroptosis." (PMID 35942174, 2022). "Cluster M0 highly expressed immunosuppressive and angiogenic phenotype-related markers (SLC40A1, NRP1, and CD36) and promote tumor progression associated with markers (CD163 and CD163L1)." (PMID 35265520, 2022). "Of note, SLC40A1 is the only discovered iron export protein in mammals, and suppressing SLC40A1 leads to iron overload and ferroptosis in various tumor cells." (PMID 35646516, 2022). "Tumor hypoxia supports such an iron-donor phenotype by upregulating solute carrier family 40, member 1 (SLC40A1) and lipocalin 2 (LCN2) expression in TAMs, resulting in increased iron availability in the TME and improved iron uptake by malignant cells." (PMID 34603327, 2021).
tumor (continued). "However, in vivo experiments using mice with differing immune status demonstrated that SLC40A1 modulates the tumor immune microenvironment." (PMID 41613134, 2026). "To summarize, SLC40A1+ TAMs exhibit pro-tumor effects as highly differentiated myeloid cells." (PMID 39232806, 2024). "It's worth noting that genes associated with metal ion regulation, including zinc regulators MT1 and MT2, which have been reported to be enriched in dysfunctional CD8 + tumor-infiltrating T cells, and iron regulators SLC40A1 and FTH1, were also found to be involved in this process." (PMID 37957625, 2023). "Moreover, the deletion of Slc40a1, encoding FPN1, in the colon epithelium resulted in enhanced tumor burden." (PMID 37273145, 2023). "miR-4735-3p facilitates ferroptosis and tumor suppression in ccRCC by targeting SLC40A1." (PMID 35646516, 2022). "High expression of SLC40A1 is positively correlated with tumor metastasis and invasion." (PMID 34793335, 2022). "In general, we demonstrate that miR-4735-3p facilitates ferroptosis and tumor suppression in ccRCC by targeting SLC40A1 and that overexpression of miR-4735-3p may prevent human ccRCC progression." (PMID 35646516, 2022). "Other candidate genes, such as Des, Ccdc108, Slc40a1, or Rftn2, also found in the Lsktm1 locus, might act synergistically with Igfbp genes to confer the tumor phenotype." (PMID 22973541, 2012). "Moreover, in HCC, TAMs express high levels of SLC40A1, a marker gene encoding ferroportin, which activates Toll-like receptor (TLR) stimulation to produce IL-1β, IL-6, and IL-23, thus shifting innate immunity processes toward tumor-favoring activity." (PMID 39766202, 2024). "Interestingly, we noticed that the expression of SLC40A1, which encodes the only known iron exporter ferroportin, is slightly but reproductively reduced upon MYCN overexpression, and RNA-seq analysis of NB tumor tissues also supports this argument." (PMID 34011924, 2021). "The interaction between ACKR2 and CCL13, CCL7 illustrates that SLC40A1+ TAMs and APOC1+ TAMs be recruited by ECs to modulate tumor immunity." (PMID 39232806, 2024). "Solute carrier family 40 member 1 (SLC40A1), also known as the iron transport protein (a tumor-suppressor protein), is closely related to the process of generality cancers." (PMID 39101131, 2024). "Compared with Mph_04_SPP1, Mph_03_DAB2 exhibiting higher levels of FOLR2, SLC40A1, and IGF1, which are genes specifically expressed by some reported TAMs that known to play a role in promoting tumor progression 57-59." (PMID 39239526, 2024). "Towards the end of the pseudotime, SLC40A1+ TAMs and APOC1+ TAMs functioning pro-tumor effects began to prevail." (PMID 39232806, 2024). "The mRNA levels of TEK, BMP1, AR, SLC11A1, SLC40A1, and F2RL1 were significantly downregulated in tumor cells compared with normal cells, and CX3CL1 and RNASE2 were upregulated in tumor cells." (PMID 35004689, 2021). "In vitro, SLC40A1 did not significantly affect tumor cell proliferation, apoptosis, or migration and invasion." (PMID 41613134, 2026). "Promoter methylation in the SLC40A1 gene has been reported to affect differential expression, and the expression of HK3 has been shown to be upregulated in CpG island methylator phenotype-high tumours, supporting our findings." (PMID 37884919, 2023). "Moreover, it is known a direct action of NRF2 on proteins involved in chemoresistance such as AKR1C1-3, ABCF2, SLC40A1, as well as on the modulation of important growth factor receptors, such as c-MET, ErbB2 and EGFR regulating tumour growth." (PMID 35453348, 2022). "SLC40A1 showed low staining intensity in normal tissues but lacked staining in tumor tissues." (PMID 37728703, 2023). "Interestingly, this cluster of macrophages also highly expressed previously reported tumor associated macrophage (TAM) related genes, including SLC40A1, although a well-defined TAM marker SPP1 was not expressed in Mono-like MAC." (PMID 37957625, 2023).
tumor (continued). "On the other hand, C3 FN1+ TCs essentially did not go beyond node 1, while C2 SLC40A1+ TCs and C3 FN1+ TCs were primarily seen in the early phases of tumor development." (PMID 40612060, 2025). "Specifically, expression levels of BCL2, SLC40A1, and TFF1 were decreased in BCa samples with respect to normal tissues, whereas APOOL and PRAME were increased in tumor samples." (PMID 37728703, 2023).
cancer (79 papers, 2013 to 2026). A tumor composed of atypical neoplastic, often pleomorphic cells that invade other tissues. "SLC40A1 plays a key role in regulating iron homeostasis and is involved in the pathogenesis of inflammatory, fibrotic, neurodegenerative diseases, and cancer, with dysfunction linked to mutations or epigenetic silencing." (PMID 42199341, 2026). "As the primary cellular iron exporter, SLC40A1 critically regulates intracellular iron homeostasis, a process implicated in tumorigenesis across multiple cancer types." (PMID 40697520, 2025). "In non-cancer studies, quercetin downregulates the ferroptosis-inhibiting SLC40A1 gene of colon cancer cells and reduces intestinal iron absorption in rats." (PMID 38892270, 2024). "miR-302a-3p and miR-4735-3p trigger the ferroptosis of the lung and renal cancer cells by downregulating SLC40A1, respectively." (PMID 38892270, 2024). "Cancer cells also suppress the expression of the iron exporter ferroportin (SLC40A1), thus enhancing iron retention inside the cells." (PMID 33425906, 2020). "miR-7-5p/ABCC1/SLC7A5, miR-107/RAD51, miR-124-3p/ABCC4/SLC16A1/MGMT, miR-212-3p/ABCG2, miR-381-3p/GJA1 and miR-485-3p/SLC40A1 may modulate pathways that confer chemoresistance to cancer cells." (PMID 40061896, 2025). "We discovered that HAMP was specifically expressed in hepatocytes and SLC40A1 was specifically expressed in macrophages in HCC and para-carcinoma tissues." (PMID 34001107, 2021). "In addition, SLC7A5 (regulated by miR-7-5p), SLC16A1 (regulated by miR-124-3p), and SLC40A1 (regulated by miR-485-3p) genes, belong to the transmembrane solute transport (SLC) and are involved in chemoresistance in many of the cancers studied here." (PMID 40061896, 2025). "Additionally, we found that TUBA1B+ TAMs, C1QC+ TAMs and IL1B+ TAMs were predominant in early-stage tumors, whereas VCAN+ TAMs, SLC40A1+ TAMs and APOC1+ TAMs had higher proportions in patients with advanced cancer." (PMID 39232806, 2024). "In cancer cells, low concentrations of compound 55 (12.5–100 nM) augmented intracellular ROS and MDA levels, depleted intracellular GSH, and decreased the expression of GPX4, SLC7A11, and SLC40A1." (PMID 36658724, 2023). "We also revealed that a subset of macrophages expressing SLC40A1 and genes reacting to various infections was present in para-carcinoma but not in HCC tissue." (PMID 34001107, 2021). "Therefore, when SLC40A1 levels increase in GBM cells, it may exert pro-cancer effect by inhibiting ferroptosis." (PMID 39039049, 2024).
infection (41 papers, 2009 to 2026). The state of being infected such as from the introduction of a foreign agent such as serum, vaccine, antigenic substance or organism. "On the other hand, the liver and kidney expression of the membrane iron exporter, Slc40a1 and Hmox1 was significantly higher in Ank1Ity16/Ity16 mice at day 0 and day 2 post infection compared to Ank1+/+." (PMID 23390527, 2013). "HO-1 that cleaves heme to release iron, Spic that is a transcription factor to promote Slc40a1 expression, and Slc40a1 that is the sole mammalian non-heme iron exporter, were associated with iron metabolism and upregulated in macrophages after the infection." (PMID 37180169, 2023). "In addition, higher expression of solute carrier family genes (Slc13a1, Slc26a3, Slc2a2, Slc40a1, Slc5a1, and Slc6a19) was seen in the gastric tissue of Muc1−/− mice compared with WT at sham and 8 h infection." (PMID 32793510, 2020). "Expression levels of SLC40A1 remained relatively stable in the trypanosusceptible Boran, while at the same time they were significantly depressed in N'Dama at 29 and 34 dpi relative to pre-infection." (PMID 19409086, 2009). "Conversely, the expression of solute carrier family members SLC7A11, glutathione peroxidase 4 (GPX4), and the iron efflux pump protein FPN1/SLC40A1 was downregulated, with this effect alleviated in the TbΔirp2 infection group." (PMID 40034497, 2025). "As the expression of slc40a1 in splenic macrophages, serum iron, TIBC, and TS% increased after the infection, accumulation of iron in the spleen is more appropriate to use as an indicator of iron overload in the spleen for our model." (PMID 37180169, 2023).
neurological disease (3 papers, 2017 to 2022).
cardiovascular disease (1 paper, 2024). "Although the crucial role of SLC40A1 in iron metabolism by facilitating the efflux of cellular iron has been confirmed, its specific molecular functions in cardiovascular diseases remain poorly understood." (PMID 38169607, 2024).
SLC40A1 also shares sentences with these, for which no sentence is quoted: Alzheimer disease (11 papers); myeloma (11); prostate carcinoma (9); Obesity (8); iron metabolism disorder (7); liver cancer (6); multiple myeloma (6); neuroblastoma (6); Salmonella Infections (6); Cerebral ischemia (5); endometriosis (5); malaria (5); bacterial infection (4); sickle cell disease (4); Stroke (4); breast tumor (3); cardiac hypertrophy (3); cardiomyopathy (3); iron overload diseases (3); melanoma (3); metabolic syndrome (3); preeclampsia (3); adrenocortical carcinoma (2); atrial fibrillation (2); Clear Cell Renal Cell Carcinoma (2); cognitive decline (2); colitis (2); colon cancer (2); colorectal cancer (2); colorectal tumors (2).
A further 84 diseases each share a sentence with SLC40A1 in 2 papers or fewer.